COL5A1 (collagen type V alpha 1 chain)
Diseases named in the same sentence as COL5A1 in open-access papers (continued):
Sharing a sentence is not in itself a finding about the gene and the disease.
glioma (14 papers, 2020 to 2025). A benign or malignant brain and spinal cord tumor that arises from glial cells (astrocytes, oligodendrocytes, ependymal cells). "The results demonstrated that (i) overexpression of COL5A1 was positively associated with larger proportions of TIDCs in all grades of gliomas and (ii) a high level of TIDCs indicated poor prognosis in gliomas." (PMID 34868960, 2021). "Currently, we are reassessing whether COL5A1 expression also meets the latest criteria as a prognostic/diagnostic factor for glioma and glioblastoma if the updated version of WHO classification of CNS tumors is formally published." (PMID 34702798, 2021). "Our Kaplan–Meier analysis demonstrated that high expression of COL1A1, COL1A2, COL3A1, COL5A1, COL8A1, ELN, FN1 resulted in lower OS in all grade glioma patients, in turn causing poor prognosis." (PMID 36106447, 2022). "High levels of NOX2 and HK2 are correlated with high levels of COL5A1 in patients with GBM relative to low-grade glioma." (PMID 35158782, 2022). "Among the mesenchymal subtype signature genes, COL5A1 is a representative gene of mesenchymal subtype cell markers in glioma." (PMID 35158782, 2022). "Next, we analyzed the expression levels of COL5A1 in NOX2-positive cells of glioma tissues from patients with GBM." (PMID 35158782, 2022). "First, we analyzed the effects of NOX2 knockdown on the change of COL5A1 gene expression in U87MG glioma cells." (PMID 35158782, 2022). "The five cancer cell lines with the highest mRNA expression of COL5A1 were chondrosarcoma, giant cell tumor, osteosarcoma, glioma, and mesothelioma." (PMID 35082969, 2022). "The effects of COL5A1 on glioma cell proliferation, migration, and invasion were verified in cellular experiments." (PMID 35082969, 2022). "In summary, COL5A1 is overexpressed in gliomas prone to malignant progression and can be used as an important marker of tumor malignancy and poor prognosis." (PMID 34868960, 2021). "Further bioinformatic analysis revealed that COL5A1 and its co-expressed genes participated in a number of pathways and biological processes involved in glioma progression." (PMID 34868960, 2021). "In our study, the role of COL5A1 in gliomas was comprehensively explored based on biological experiments and bioinformatics analysis for the first time." (PMID 34868960, 2021). "The results of flow cytometry in this study demonstrated that decreased COL5A1 improved the percent of glioma cells at the G1 phase." (PMID 34868960, 2021). "In order to explore the prognostic value of COL5A1 in gliomas, expression profiles and clinical information of glioma samples from the CGGA and TCGA databases were retrieved for prognosis analysis." (PMID 34868960, 2021). "To assess the biological functions of COL5A1 in gliomas, we performed gene set enrichment analysis (GSEA) based on mRNA expression profiles of 173 glioblastomas from the TCGA database." (PMID 34868960, 2021). "In the present study, we investigated the expression levels of COL5A1 in gliomas with different grades or pathological types based on public data and clinical samples." (PMID 34868960, 2021). "The TIMER database was used to evaluate the relationships between the expression levels of COL5A1 and the abundance of TIICs in gliomas based on the TCGA database." (PMID 34868960, 2021). "We found that the overexpression of COL5A1 was positively correlated with the increasing tumor malignancies and indicated poor prognosis in gliomas." (PMID 34868960, 2021). "Finally, we evaluated the tumor-infiltrating immune cells of gliomas depending on COL5A1 and found that the percentages of the dendritic cells, which were known as the central mediator of tumor microenvironment in gliomas, were positively associated with the expression levels of COL5A1." (PMID 34868960, 2021).
glioma (continued). "In general, GO categories related to regulation of ECM stand out among function enrichment analyses, indicating that COL5A1 promotes glioma progression mainly through organization of ECM or activating ECM receptors." (PMID 34868960, 2021). "Given its prognostic value, biological functions, and relationship with tumor-infiltrating immune cells, COL5A1 is a reliable biomarker and potential therapeutic target of gliomas." (PMID 34868960, 2021). "After IHC scoring, we observed that COL5A1 was increased at the protein level in low-grade glioma and GBM patients." (PMID 34702798, 2021). "In lower-grade glioma, COL3A1, COL4A1, and COL5A1 are associated with patient prognosis and tumor progression." (PMID 34691289, 2021). "On the other hand, aldolase C (ALDOC) and cytochrome oxidase subunit 7A2 (COX7A2), which were both negatively co-expressed genes of COL5A1, were good prognostic factors of gliomas." (PMID 34868960, 2021). "COL5A1 is overexpressed in gliomas with more malignant features and plays an oncogenic role in tumor cells’ proliferation, migration, and chemoresistance to TMZ." (PMID 34868960, 2021). "The specific COL5A1 small interfering RNA was used to exploit the therapeutic potential of inhibiting COL5A1 in gliomas." (PMID 34868960, 2021). "Downregulation of COL5A1 was proved to inhibit proliferation and migration of glioma cells for the first time in our study." (PMID 34868960, 2021). "In particular, several collagen-related genes (e.g., COL1A1, COL3A1, COL5A1) were significantly upregulated, suggesting increased extracellular matrix deposition and the establishment of an immunosuppressive microenvironment in Grade 4 gliomas." (PMID 41432874, 2025). "Earlier bioinformatics research suggested that reducing COL5A1 expression could inhibit glioma cell proliferation and migration and increase sensitivity to the chemotherapeutic drug temozolomide." (PMID 39850883, 2024). "Our results showed that NOX2 promotes the elevation of COL5A1 expression in human glioma cells." (PMID 35158782, 2022). "The human glioblastoma cell line U251 was used to confirm whether COL5A1 knockdown could impact the growth of glioma cells." (PMID 35082969, 2022). "Next, we investigated whether NOX2-dependent high glycolytic activity could affect the gain of the COL5A1-mediated mesenchymal phenotype in human glioma cells." (PMID 35158782, 2022). "A number of COL5A1 co-expressed genes mentioned in this study have been studied in gliomas." (PMID 34868960, 2021). "We also evaluated the levels of COL5A1 in gliomas according to their isocitrate dehydrogenase (IDH) mutation and 1p/19q co-deletion status, which served as important molecular markers for identifying glioma subtypes." (PMID 34868960, 2021). "The recurrent gliomas exhibited higher levels of COL5A1 than the primary ones (p < 0.05)." (PMID 34868960, 2021). "Additionally, the survival analysis of this study demonstrated that the high expression level of COL5A1 correlated with poor prognosis of glioma patients." (PMID 34868960, 2021). "Additionally, we evaluated the effect of COL5A1 on the abundance and distribution of TIICs in gliomas." (PMID 34868960, 2021). "Furthermore, cell experiments were conducted to examine the effects of downregulating COL5A1 in glioma cells on cell phenotypes such as proliferation, migration, and chemoresistance to TMZ." (PMID 34868960, 2021). "Taken together, COL5A1 is an important biomarker and potential therapeutic target of gliomas." (PMID 34868960, 2021). "We found that COL5A1 expression was correlated with poor survival in glioma patients (p = 0.031)." (PMID 34702798, 2021). "We performed immunohistochemical (IHC) staining with an anti-COL5A1 antibody in our glioma cohort." (PMID 34702798, 2021). "Meanwhile, high amounts of TIDCs indicated worse prognosis in LGG and GBM, implying that COL5A1 may participate in the formation of immunosuppressive TME in gliomas." (PMID 34868960, 2021).
glioma (continued). "In addition, the elevation of COL5A1 correlates with poor survival in patients with glioma." (PMID 35158782, 2022). "Additionally, the role of COL5A1 in glioma cells was verified in vitro experiments." (PMID 35082969, 2022). "However, the biological functions of COL5A1 in gliomas are still unclear." (PMID 34868960, 2021). "We also found that downregulation of COL5A1 could sensitize glioma cells’ response to TMZ." (PMID 34868960, 2021). "Moreover, downregulation of COL5A1 could inhibit proliferation and migration of glioma cells and enhance their temozolomide sensitivities in vitro." (PMID 34868960, 2021). "The number of cells showing subcellular co-localization of COL5A1 and NOX2 was significantly increased in patients with GBM (G4) and G3 glioma (G3) compared to that in G1 and G2 glioma." (PMID 35158782, 2022). "The expression levels of COL5A1 and COL5A2 are significantly correlated with glioma progression stage." (PMID 35198102, 2022). "The intensity of COL5A1-positive staining was increased in patients with GBM (G4) and G3 glioma (G3) compared to that in patients with G1 and G2 gliomas (G1, G2)." (PMID 35158782, 2022). "Especially in the GBMs (WHO IV), COL5A1 was more highly expressed than the grade II and III gliomas dramatically (p < 0.001)." (PMID 34868960, 2021). "Moreover, NOX2 increases the expression of mesenchymal-subtype-related genes, including COL5A1 and FN1 in U87MG glioma cells." (PMID 35158782, 2022). "Similarly, the number of cells showing subcellular co-localization of COL5A1 and HK2 was increased in patients with GBM (G4) and G3 glioma compared to that in G1 and G2 glioma." (PMID 35158782, 2022). "Notably, the intensity of COL5A1-positive staining and the number of cells showing subcellular co-localization of COL5A1 and NOX2 or HK2 were significantly elevated in in patients with GBM (G4) relative to that in patients with G3 glioma (G3)." (PMID 35158782, 2022). "In this study, the function enrichment analysis based on COL5A1 and its co-expressed genes concluded a number of significant KEGG pathways and GO categories participating in the malignant behavior of proliferation, invasion, and migration in gliomas." (PMID 34868960, 2021). "In glioma tissues of GBM, mesenchymal subtype cells have the high expression of mesenchymal subtype signature genes, including chitinase 3 like 1 (CHI3L1), collagen type V alpha 1 chain (COL5A1), fibronectin 1 (FN1), cyclin B1 (CCNB1), and maternal embryonic leucine zipper kinase (MELK)." (PMID 35158782, 2022). "Recent studies found COL5A1 was positively correlated with the increasing malignancy of glioblastoma through the PPRC1-ESM1 axis activation and extracellular matrix remodeling, and it may be a potential therapeutic target for glioma." (PMID 35800363, 2022). "Intriguingly, a high expression of COL5A1 was mainly enriched in the KEGG pathways of the ECM receptor interaction, complement and coagulation cascades, focal adhesion, and glycosaminoglycan biosynthesis keratan sulfate, which were all related to progression or chemoresistance of glioma cells." (PMID 34868960, 2021). "The other well-predicted genes, including COL5A1, CPA4, CSTB, and PPIC in gliomas and DAK, ITPRIP, TM4SF19, TMEM200A in RCC have not been studied thoroughly in cancer and their roles in cancer worth further investigating." (PMID 32194984, 2020).
glioblastoma (11 papers, 2014 to 2025). The most malignant astrocytic tumor (WHO grade IV). "Correction to: Glioblastoma induces CAF-like astrocyte activation via the AKT/mTOR-SERPINH1/COL5A1 axis This corrigendum corrects the authors' affiliations to: Jingxian Zhang1,2#, Yajia Chen1,2#, and Hongwu Xu1,2*." (PMID 40819264, 2025). "COL5A1 was described as biomarker of poor prognosis, promoting glioblastoma progression via the PPRC1-ESM1 axis, and a mesenchymal-subtype-related gene." (PMID 35806337, 2022). "Since TMZ was reported to cause senescence and apoptosis in glioblastoma, we compared the apoptosis ratios of U87 cells exposed to 50 μg/ml TMZ from three groups and found that inhibition of COL5A1 could enhance apoptosis induced by TMZ significantly." (PMID 34868960, 2021). "In glioblastoma, we identified an RND1low signature of six genes (ITGA5, COL3A1, COL5A1, MET, COL1A2, LAMC1), upregulated in glioblastoma patients with low RND1, that predicts the overall survival of glioblastoma patients." (PMID 31344837, 2019). "These include previously identified HIF-1 target genes such as ANKRD37, STC-2, and STC-1, as well as COL5A1 induced by hypoxia in the ventricle, ZNF395 regulated by hypoxia in glioblastoma, and TMEM45 in hematopoietic stem cells." (PMID 25122487, 2014). "Based on all of the evidence, our data suggest that COL5A1 may be a novel prognostic target and that the COL5A1−PPRC1−ESM1 axis is a promising therapeutic target for malignant glioblastoma." (PMID 34702798, 2021). "Finally, based on signaling pathways activated in patients with low levels of RND1, we identified an RND1low signature of six genes (MET, LAMC1, ITGA5, COL5A1, COL3A1, COL1A2) that is an independent prognostic factor in glioblastoma." (PMID 30333910, 2018). "For example, STCs exhibited, compared to STPs, the overexpression of several markers of the mesenchymal subtype of glioblastoma, such as COL1A1, COL1A2, COL5A1, IGFBP6, DCBLD2, many of which are also typically expressed by microglia or reactive astrocytes in glioblastoma microenvironment." (PMID 26188123, 2015).
melanoma (8 papers, 2017 to 2025). A malignant, usually aggressive tumor composed of atypical, neoplastic melanocytes. "Meanwhile, a study of malignant melanoma found that mutations in COL5A1 were linked to the infiltration of CD8+ T cells and activated NK cells." (PMID 35069551, 2021). "The ECM component COL5A1 has already been determined to be associated with BRAFi resistance in melanoma." (PMID 34885166, 2021). "It was interesting to note that lower expression of COL5A1 was also detected in bladder, colorectal, kidney, leukemia, melanoma, ovarian, sarcoma, and prostate cancer datasets." (PMID 35082969, 2022). "In addition, COL5A1 is regarded as a novel biomarker that determines sensitivity to ICB therapies in melanoma." (PMID 35082969, 2022). "In the same study, other genes such as COL5A1, periostin (POSTN), thrombospodin 2 (THBS2) and LOX were upregulated and associated with poor survival after adjuvant chemotherapy; these genes were also upregulated in our melanoma case series." (PMID 28743863, 2017).
keloid (7 papers, 2021 to 2025). An irregularly shaped, elevated mark on the skin caused by deposits of excessive amounts of collagen during wound healing. "Isolated deep lesional fibroblasts display elevated expressions of collagen type I alpha 1 chain (COL1A1), consistent with our findings where COL1A1, COL1A2, COL4A1, and COL5A1 were prominently upregulated in keloid tissues." (PMID 41562114, 2025). "The results of the FOXP1-Cut&Tag experiment in keloid fibroblasts revealed that FOXP1 is associated with the SEs of SERPINH1, MMP14, COL5A1, COL16A1, and SPARC, all of which exhibited significant signal enrichment in their SE regions." (PMID 40702440, 2025). "The diagnostic value of COL1A1, COL1A2, COL3A1, COL5A1, and COL5A2 between keloid and different control tissue was evaluated by different datasets." (PMID 35872873, 2022). "We clustered collagen gene expression in keloids and lymphedema and found that keloid tissue tended to have higher expression of COL3A1, COL1A2, COL1A1, COL6A1, and COL5A1 than did the ML and SL groups." (PMID 40742741, 2025). "It was downregulated in keloid and can negatively regulate the expression of COL1A1, COL1A2, COL3A1, COL5A1, and COL5A2." (PMID 35872873, 2022). "In our study, the results of ENCORI prediction and RT-qPCR showed that miR-29a-3p can regulate the expression of COL1A1, COL1A2, COL3A1, COL5A1, and COL5A2, and these target genes were closely related to the development of keloid." (PMID 35872873, 2022). "When the diagnostic value of these key genes were evaluated between the normal skin from keloid-prone or normal individuals (GSE113619), the AUC values of COL1A1, COL1A2, COL3A1, COL5A1, and COL5A2 in keloid were 0.650, 0.625, 0.575, 0.525, and 0.450, respectively." (PMID 35872873, 2022). "Our study provides a novel mechanism insight whereby the dysregulation of COL5A1 and COL5A2 might be involved in the keloid pathogenesis." (PMID 33860039, 2021). "However, there is no research report on the correlation between COL5A1 and COL5A2 expression and keloid so far." (PMID 35872873, 2022).
liver fibrosis (7 papers, 2015 to 2025). "Moreover, the mRNA expression levels of asma, Tgfβ, Col2a1, and Col5a1 were increased in the liver of SD mice, suggesting an increased tendency to liver fibrosis." (PMID 38633246, 2024). "Also, incubating LX2 cells with either GDF11 or TGF-β for 24 h led to significantly elevated mRNA levels of MMP2, αSMA/ACTA2, Col1A1 and Col5A1 — markers for stellate cell activation and liver fibrosis." (PMID 33126224, 2020). "In our study, COL5A1 expression in cirrhosis was higher than in CHB, which indicated that COL5A1 might play important roles in the initiation and activation of liver fibrosis as well as the regulation of immune responses." (PMID 30925583, 2019).
bladder cancer (6 papers, 2019 to 2025). "As such, COL5A1, COL8A1 and TGFB1I1 can serve as the prognosis biomarkers for patients of bladder cancer." (PMID 30723390, 2019). "In this study, we selected four hypoxia-related genes that were highly related to bladder cancer patients’ survival status, including ANXA2, GALK1, COL5A1, and HS3ST1, to construct a signature and this signature is independent of other clinical characteristics." (PMID 34026819, 2021). "COL5A1, COL8A1 were most significant in the prediction of the bladder cancer’s prognosis(P-value< 0.01), and may serve as the therapeutic target for the disease." (PMID 30723390, 2019).
cervical cancer (6 papers, 2019 to 2024). A primary or metastatic malignant neoplasm involving the cervix. "The aberrant expression of many of them were positively correlated with the risk of cervical cancer, with the KM curves of four conveying significance, including COL4A1, COL4A2, COL5A1, and COL12A1, which implied their potential application in clinical diagnosis." (PMID 36683048, 2023). "Our data revealed a close positive correlation between the expression of P4HA2 and collagen biosynthesis-related genes (Col4A1, Col5A1 and Col6A1) in cervical cancer, which is also consistent with a previous report of a positive correlation between collagen biosynthesis and P4HA2 in breast cancer." (PMID 32226497, 2020). "Collagen members, including COL6A3, COL5A1, and COL8A1, act as oncogenes in the progression of different types of cancer and are highly correlated with poor prognosis in cervical cancer patients." (PMID 32523603, 2020).
Marfan syndrome (6 papers, 2013 to 2025). A disorder of the connective tissue. "COL5A1 mutations result in abnormal type V collagen production, leading to symptoms that resemble certain aspects of Marfan syndrome." (PMID 41411243, 2025). "Patient AN_002535, who carried the large genomic duplication in COL5A1, exhibited skeletal signs of Marfan syndrome and other unusual signs." (PMID 23587214, 2013). "In our dataset, none of the 26 COL5A1 rare LoF carriers overlapped with diagnosed Marfan syndrome patients, highlighting the limitations of traditional rare variant association methods in detecting such associations." (PMID 41411243, 2025). "Moreover, as supported by the literature, several have been associated with hernia formation, Ehlers–Danlos syndrome, and Marfan’s syndrome (e.g., COL1A1, COL3A1, COL5A1, FBN1, and TIMP1)." (PMID 22648066, 2013).